S100B (S100 calcium binding protein B)
Description:
Small zinc- and- and calcium-binding protein that is highly expressed in astrocytes and constitutes one of the most abundant soluble proteins in brain. Weakly binds calcium but binds zinc very tightly-distinct binding sites with different affinities exist for both ions on each monomer. Physiological concentrations of potassium ion antagonize the binding of both divalent cations, especially affecting high-affinity calcium-binding sites (By similarity). Acts as a neurotrophic factor that promotes astrocytosis and axonal proliferation (By similarity). Involved in innervation of thermogenic adipose tissue by acting as an adipocyte-derived neurotrophic factor that promotes sympathetic innervation of adipose tissue (By similarity). Binds to and initiates the activation of STK38 by releasing autoinhibitory intramolecular interactions within the kinase (By similarity). Could assist ATAD3A cytoplasmic processing, preventing aggregation and favoring mitochondrial localization. May mediate calcium-dependent regulation on many physiological processes by interacting with other proteins, such as TPR-containing proteins, and modulating their activity.
Synonyms: S100beta; NEF; S100; S100-B
Tractability: Small molecule: a structure with a bound ligand is known; a high-quality ligand is known; it has a binding pocket of medium quality; it belongs to a druggable protein family. Antibody: its Gene Ontology location is reachable by antibodies, with high confidence; UniProt places it where antibodies can reach, with medium confidence. PROTAC: its protein half-life has been measured; a small molecule that binds it is known.
Target class: Other cytosolic protein
Gene: Protein-coding gene on chromosome 21 (46,598,508 to 46,605,208, reverse strand). Ensembl gene ENSG00000160307.
Subcellular location: Cytoplasm; Nucleus; Secreted
Subcellular location (Human Protein Atlas): Cytosol; Primary cilium; Vesicles; Basal body; Cytokinetic bridge; Microtubules; Mitotic spindle; Nucleoplasm; Predicted to be secreted
Pathways (Reactome):
Immune System: Advanced glycosylation endproduct receptor signaling; TAK1-dependent IKK and NF-kappa-B activation; TRAF6 mediated NF-kB activation
Signal Transduction: Nuclear signaling by ERBB4
Gene Ontology:
Molecular function: calcium ion binding; calcium-dependent protein binding; identical protein binding; protein binding; protein homodimerization activity; RAGE receptor binding; S100 protein binding; zinc ion binding; tau protein binding; signaling receptor binding
Biological process: positive regulation of canonical NF-kappaB signal transduction; adaptive thermogenesis; axonogenesis; central nervous system development; learning or memory; positive regulation of cell population proliferation; sympathetic neuron projection extension; astrocyte differentiation; cellular response to hypoxia; long-term synaptic potentiation; negative regulation of skeletal muscle cell differentiation; neuron projection extension; positive regulation of apoptotic process; positive regulation of myelination; positive regulation of neuron differentiation; positive regulation of synaptic transmission; regulation of cell shape; response to anesthetic; response to ethanol; response to glucocorticoid; response to methylmercury
Cellular component: cytoplasm; cytosol; nucleoplasm; nucleus; perinuclear region of cytoplasm; ruffle; extracellular region; neuronal cell body
Genetic constraint (gnomAD): Loss-of-function variants: 4 observed, 5.98 expected, observed/expected ratio (o/e) 0.67, 90% interval 0.33 to 1.49. That is too few expected variants to judge how well the gene tolerates losing a copy. Missense variants: 84 observed, 103.16 expected, observed/expected ratio (o/e) 0.81, 90% interval 0.68 to 0.98. Synonymous variants: 31 observed, 37.81 expected, observed/expected ratio (o/e) 0.82, 90% interval 0.62 to 1.11.
Homologues: Orthologues: macaque S100B (99% identical), mouse S100b (99% identical), rabbit S100B (99% identical), rat S100b (98% identical), guinea pig S100B (97% identical), zebrafish s100b (61% identical). Paralogues in human: S100A1 (58% identical), S100P (49% identical), S100A4 (45% identical), S100Z (45% identical), S100A5 (43% identical), S100A2 (42% identical), S100A3 (39% identical), S100A6 (39% identical), S100A9 (39% identical), S100A10 (37% identical), S100A12 (36% identical), S100A11 (35% identical), and 9 more.
Diseases named in the same sentence as S100B in open-access papers:
S100B is named in the same sentence as 418 diseases in open-access papers, as found by Europe PMC text mining. Sharing a sentence is not in itself a finding about the gene and the disease. The quoted sentences say what the papers report.
melanoma (220 papers, 2004 to 2026). A malignant, usually aggressive tumor composed of atypical, neoplastic melanocytes. "AHNAK2 is expressed in all muscle cells, and its encoded protein interacts with S100B and other proteins to participate in cell structure and calcium signal transduction, and is related to melanoma." (PMID 41479783, 2025). "The results of multivariable analyses showed that increased plasma levels of S100B at advanced melanoma diagnosis were independently associated with MBM development besides the first-line treatment." (PMID 40217072, 2025). "Elevated levels of S100B have been identified in patients with metastatic melanoma and patients with tumor relapse from melanoma, and are associated with impaired OS." (PMID 40217072, 2025). "Exosomal MIA and S100B levels were also higher in late-stage melanoma patients and associated with shorter survival." (PMID 39156972, 2024). "Elevated baseline S100B levels are also associated with decreased OS in late-stage melanoma patients receiving anti-PD-1 and anti-CTLA-4 therapeutic interventions." (PMID 39156972, 2024). "It is noteworthy that combination of elevated serum S100B and Breslow tumour thickness of >4 mm increased the diagnostic accuracy for detecting metastatic disease in melanoma." (PMID 37664072, 2023). "Regarding the diagnostic impact, elevated S100B levels emerged as a more reliable marker for predicting relapse in melanoma patients at various stages compared to elevated LDH levels." (PMID 38202181, 2023). "S100B protein is a calcium-binding protein expressed in melanoma cells and proposed as a diagnostic biomarker." (PMID 37292567, 2023). "A correlation between S100B serum levels and tumor growth has been reported in melanoma patients, where decreased levels were associated with clinical response to therapy." (PMID 37948527, 2023). "Biomarkers such as melanoma-associated antigens (MAAs), S100B, microRNAs (miRNAs), and circulating tumor cells (CTCs) have the potential to aid in the detection, diagnosis, and prognosis of melanoma." (PMID 37292567, 2023). "S100B has garnered increased attention among researchers as a diagnostic marker for melanoma, due to its significantly higher expression and secretion in malignant tissue compared to healthy tissue." (PMID 38202181, 2023). "Overexpression of RAGE induced melanoma cells to become more metastatic by triggering cells into mesenchymal-like morphologies, which is associated with the upregulation of its ligand S100B, a calcium-binding protein." (PMID 35162934, 2022). "S100B protein served as a well-analyzed biomarker in melanoma and performed well in detecting early disease progression in high-risk melanoma patients." (PMID 35646893, 2022). "The enrichment of MIA and S100B in exosomes of melanoma patients indicated their potential value as diagnostic and prognostic markers." (PMID 36704194, 2022). "In the diagnosis of melanoma, the determination of serum S100B is a marker of greater diagnostic utility than classic markers such as lactate dehydrogenase or alkaline phosphatase." (PMID 36235175, 2022). "The only meta-analysis conducted in 2008 found that elevated serum S100B levels were associated with significantly worse survival in melanoma patients." (PMID 34950582, 2021). "A disadvantage of S100B as a tumor marker of malignant melanoma is the possible loss of S100B expression during malignant progression which would disrupt the dependency of measured serum S100B levels to the cell loss fraction and immunologic cell death." (PMID 32188047, 2020). "The presence of a P/LP germline variant remained an independently significant factor for melanoma specific survival in the multivariate Cox regression analysis, along with serum S100B and LDH." (PMID 32354124, 2020).
melanoma (continued). "They observed that MIA and S100B can be detected in EXOs and their quantification presents diagnostic and prognostic utility in melanoma patients." (PMID 33050185, 2020). "S100B is described to be a prognostic marker for the advanced stages of melanoma, especially for distant metastasis, and increased serum S100B levels are associated with shorter disease-free survival (DFS) and OS." (PMID 32722137, 2020). "Serum levels of S100β are associated with tumor burden, poor prognosis and poor response to treatment in melanoma patients." (PMID 30973923, 2019). "Several other circulating proteins have shown diagnostic and prognostic value for melanoma, including S100B, C reactive protein (CRP) and melanoma-inhibiting activity (MIA) protein but all have limitations in routine clinical use." (PMID 29343260, 2018). "Elevated S100B level is a clinically used diagnostic biomarker for several brain pathologies and melanoma." (PMID 27159591, 2016). "Our previously published results have shown that in adult melanoma patients, there is a strong correlation between S100B and melanoma inhibitory activity (MIA) and that this association matches an unfavorable clinical evolution." (PMID 32309563, 2015). "S100B, a subunit of the S100 protein family, is detectable in the serum of melanoma patients and has been associated with tumour resistance and disease progression." (PMID 27429260, 2014). "FDG PET/CT is more sensitive and more specific in detection of metastases in high risk melanoma patients compared to the tumor markers S100B and MIA." (PMID 21935432, 2011). "Other serum biomarkers of interest in melanoma include S100B, melanoma-inhibiting activity (MIA), and tumor-associated antigen 90 immune complex (TA90IC)." (PMID 22220281, 2011). "This study demonstrates the superior prognostic value of FDG PET/CT and its higher power to discriminate between patient groups with different mortality risk in high risk melanoma compared to the tumor markers S100B and MIA." (PMID 21935432, 2011). "In a study of 105 patients with stage IV melanoma, elevated serum levels of S100B were associated with a significantly shorter survival." (PMID 19859558, 2010). "Elevated S100B levels and stage IV disease at advanced melanoma diagnosis might indicate an increased risk of MBM development." (PMID 40217072, 2025). "Moreover, when calprotectin was combined with established melanoma biomarkers S100B and LDH, the diagnostic accuracy for identifying metastatic disease improved substantially." (PMID 40869349, 2025). "Elevated S100B levels have been linked to worse outcomes in melanoma." (PMID 40981345, 2025). "In addition, distant metastases were significantly more likely to be associated with elevated serum S100B levels in patients with BRAF mutant melanoma than in patients with BRAF wild-type melanoma." (PMID 39272837, 2024). "Finally, S100b inhibition decreased cell viability and increased susceptibility of melanoma cells to the chemotherapeutics." (PMID 36899866, 2023). "Elevated S100B levels have been associated with significantly worse survival in melanoma patients." (PMID 38202181, 2023). "Furthermore, elevated serum S100B levels were associated with melanoma metastasis, and lower serum S100B levels were associated with improved survival." (PMID 35785160, 2022). "Likewise, elevated serum levels of S100B have demonstrated to have a prognostic value in both metastatic and high-risk resected melanoma settings." (PMID 36613491, 2022). "Additionally, serum of S100B is used as the diagnostic biomarker for melanoma for a long time, which has also been adopted to be the candidate predicting factor for lung cancer brain metastasis recently." (PMID 34712325, 2021). "By contrast, S100B shows a strong association with melanoma prognosis." (PMID 32013263, 2020).
melanoma (continued). "Activation of RAGE by S100A4, S100A7, S100A8, S100A9, S100A14, S100B, and S100P was associated with upregulation of NF-κB that induced progression of different types of cancer including pancreatic, melanoma, breast, prostate, colon, neuroblastoma, and esophageal." (PMID 32443845, 2020). "The only biomarker included in the AJCC staging system is lactate dehydrogenase (LDH), the strongest independent prognostic factor for stage IV melanoma, although an important increase in serum S100β levels has been associated to metastatic progression, irrespective of stage." (PMID 27216146, 2016). "S100B released from melanoma cells is a damage-associated molecular pattern protein that may contribute to tumour-associated inflammation and activate signalling pathways in tumour cells via receptors for advanced glycation end products, thereby promoting melanoma progression." (PMID 37664072, 2023). "The conformational change in chromatin state may be best linked to S100B upregulation in melanoma." (PMID 36899866, 2023). "S100B downregulation is consistent with the observed destruction of melanoma cells, which are usually S100+." (PMID 41514118, 2026). "While S100B is primarily a glial marker, it is also expressed by melanocytes, from which melanoma tumor cells originate, and its expression in melanoma reflects a cellular origin in the neural crest." (PMID 40217072, 2025). "To guide ROIs selection, we stained the tissues using antibodies targeting S100B/PMEL for melanoma cells, CD45 for immune cells and SYTO13 nucleic acid stain." (PMID 41168392, 2025). "It is possible that, in some cases, as melanoma progresses and S100B levels increase, a decrease in lymphocyte counts can occur due to the suppression of the immune system by the cancer." (PMID 40535809, 2025). "Here, a peptide-based fluorescentbiosensing system was developed for the sensitive and rapid detectionof S100B, a key prognostic biomarker for melanoma." (PMID 41196004, 2025). "Serum S100B has also shown utility as an early indicator of treatment response in melanoma patients receiving immunotherapy." (PMID 40981345, 2025). "For example, S100B is commonly employed in Germany for melanoma surveillance, but its limited global validation has precluded widespread use." (PMID 40717879, 2025). "A recent meta-analysis of melanoma follow-up studies found that S100B surpassed LDH in detecting recurrence, demonstrating a higher area under the curve (AUC) and greater sensitivity while maintaining high specificity." (PMID 40981345, 2025). "After pathological analysis, skin tissues that were potentially melanoma positive were then stained with the melanoma marker S100B to confirm melanoma formation." (PMID 40501869, 2025). "In this work, immunosensor was fabricated for sensitive detection of the melanoma biomarker S100B based on enhanced electrochemiluminescence (ECL) via electronic metal-support interactions." (PMID 41459192, 2025). "Herein, we developed a highly sensitivedetection platform forthe melanoma biomarker S100B, where a fluorescently labeled peptide-nucleicacid (PNA) beacon, with the peptide TRTK12 as the biorecognition element,has been engineered." (PMID 41196004, 2025). "S100B’s role as a potential prognostic biomarker in melanoma stems from its involvement in disease progression." (PMID 39766118, 2024). "Studies determining the S100B tumor marker in lower stages of melanoma have also been published, but these results are inconsistent in terms of their relationship to prognosis." (PMID 39387479, 2024). "SP‐01 highly mimicked MPNSTs histologically but expressed S100B, p75, and SOX10 neural crest markers, like melanomas, and presented a high mutation frequency, mostly associated with the skin cancer COSMIC mutational signature." (PMID 37798904, 2024).